EML4 (EMAP like 4)
Diseases named in the same sentence as EML4 in open-access papers (continued):
Sharing a sentence is not in itself a finding about the gene and the disease.
lung cancer (continued). "EML4–ALK-positive (ALK+) lung cancers are treated with targeted ALK inhibitors as the current standard of care." (PMID 38458397, 2024). "Adenocarcinoma with positive echinoderm microtubule-associated protein-like 4 gene and anaplastic lymphoma kinase (EML4-ALK) gene fusion accounts for 3-7% of lung cancer cases and can be targeted with ALK tyrosine kinase inhibitors (TKIs)." (PMID 39267820, 2024). "Translocation between the N-terminal of echinoderm microtubule-associated protein-like 4 (EML4) and ALK gene leads to EML4-ALK formation which has carcinogenic and malignant features and occurs in 80% of ALK positives in lung cancer." (PMID 38234663, 2024). "EML4 was the most frequent partner of ALK fusions in lung cancers, while NPM1 was the case in lymphomas." (PMID 38877018, 2024). "Although we focus on oncogenic EGFR-driven lung adenocarcinomas, our findings appear to extend to other molecular subsets such as EML4-ALK-driven lung cancer and likely reflect a more general principle of targeted therapy-induced adaptability." (PMID 38049664, 2024). "In 2007, the ALK gene rearrangement in NSCLC patients revealed the initial fusion between echinoderm microtubule-associated protein-like 4 (EML4) and ALK in lung cancer." (PMID 38397899, 2024). "Although several cell lines have been used in the study of EML4-ALK-positive lung cancer, the number of cancer models remains limited." (PMID 38829559, 2024). "First, lung cancer patient cell lines, H3122 and H2228, that express EML4–ALK V1 and V3, respectively, were examined." (PMID 38458397, 2024). "Despite BRAF gene mutations in lung carcinoma being identified before EML4-ALK translocations, there have been few clinical studies completed on this type of lung carcinoma with BRAF mutation." (PMID 39199653, 2024). "Common genetic mutations in lung carcinoma include EGFR, KRAS, EML4-ALK, Ros1, and c-MET, among others." (PMID 38571504, 2024). "We report a case in which the EML4-ALK fusion gene was successfully detected from a sputum sample using the LCCP that was just released in Japan as a new next-generation sequencing lung cancer panel, CDx." (PMID 37510070, 2023). "This dependence of EML4-ALK protein stability on activity was also observed in EML4-ALK driven lung cancer cell lines." (PMID 38264745, 2023). "Studies have demonstrated the oncogenic potential of EML4–ALK in the development of lung cancer in mice." (PMID 38077251, 2023). "We have recently reported the development of murine Eml4-Alk-driven lung cancer cell lines that readily form orthotopic lung tumors in C57BL/6 mice." (PMID 37470475, 2023). "Herein, we used three murine models of EML4-ALK lung cancer to test the role for host immunity in the alectinib therapeutic response." (PMID 36739466, 2023). "Crizotinib‐resistant cell lines derived from EML4‐ALK+ lung cancer showed elevated levels of EGFR, HER2 and HER3 phosphorylation." (PMID 37149843, 2023). "Although primary lung cancers and paired BMs shared pivotal molecular phenotypes, such as the EGFR expression and EML4-ALK fusion status in lung cancer cases." (PMID 37384291, 2023). "In lung cancer, two f-circRNAs derived from EML4::ALK fusion have been identified, and proposed as a liquid biopsy biomarker, whereas another f-circRNA from SLC34A2::ROS1 translocation was proven to boost cancer cell migration." (PMID 36585787, 2023). "In summary, the emerging evidence of LLPS in ALK fusions, particularly EML4-ALK variant 1, emphasizes the significance of this cellular process in the pathogenesis of lung cancer." (PMID 37705755, 2023). "Lung cancers bearing oncogenic EML4-ALK fusions respond to targeted tyrosine kinase inhibitors (TKIs; e.g., alectinib), with variation in the degree of shrinkage and duration of treatment (DOT)." (PMID 36739466, 2023). "Choroidal metastasis as an initial presenting feature of lung cancer with EML4-ALK translocation is exceedingly rare and greatly impacts patient quality of life (QOL)." (PMID 35433411, 2022).
lung cancer (continued). "The fusion of ALK with echinoderm microtubule-associated protein like-4 (EML4) gene creates the fusion gene EML4-ALK, which is the most observed ALK fusion in lung cancer." (PMID 36230484, 2022). "Few groups reported that lung cancer patients with fusion genes, especially EML4-ALK were younger than those without, which was in parallel with our data." (PMID 35428753, 2022). "In contrast, H2228 cells (EML4-ALK V3) showed the most resistance of all lung cancer cell lines examined to vincristine with around 20-fold higher IC50 compared with H3122 cells." (PMID 35159046, 2022). "It is well established that lung cancer patients harbour many driver gene mutations, such as K-ras, EGFR, EML4-ALK, and CLIP1-LTK, which contribute to the initiation and progression of lung cancer." (PMID 35574342, 2022). "ALK fusions in non-lung cancer patients were more commonly fused with non-EML4 partners (Bonferroni’s post-test, P < 0.0001)." (PMID 36369474, 2022). "EML4-ALK is an oncogenic fusion protein present in approximately 5% of non–small cell lung cancers (NSCLC)." (PMID 35656694, 2022). "Although GEM models for EML4‐ALK lung cancer were first established in 2008, the use of GEM models to assess the in vivo potency of ALK TKIs was limited due to technical challenges." (PMID 34845836, 2022). "The fusion gene of echinoderm microtubule-associated protein-like 4 (EML4) and the ALK gene was discovered in lung cancer cells in 2007." (PMID 35337281, 2022). "Of the 31 ALK fusion events detected in non-lung cancers, including gastrointestinal and gynecological cancers, 11 patients (35.5%) were detected with EML4-ALK fusions." (PMID 36369474, 2022). "Here, we developed a GEM model specifically for EML4‐ALK lung cancer and found that XMU‐MP‐5 led to strong tumor regression resulting from ALK activity inhibition and tumor cell apoptosis." (PMID 34845836, 2022). "The most common EML4-ALK fusion variants are 1 and 3, which together account for about 60% of EML4-ALK-positive lung cancer cases." (PMID 34633654, 2022). "Different classes of ALK tyrosine kinase inhibitors (TKI) are available but used exclusively for EML4-ALK (+) lung cancers." (PMID 33466277, 2021). "This patient has lung adenocarcinoma positive for EML4-ALK fusion gene, but the treatment outcome is obviously different from that of other patients with lung cancer positive for EML4-ALK fusion gene." (PMID 34034462, 2021). "Among the 5 ALK-positive cases with lung cancer, the following variants were identified: three (60%) exhibited EML4-ALK-V3a fusion (cases 3, 4 and 5), one (20%) exhibited EML4-ALK-V5p fusion (case 5) and two (40%) exhibited EML4_ex13 fusion (cases 1 and 2)." (PMID 34234236, 2021). "Nowadays, different classes of ALK tyrosine kinase inhibitors (TKI) are available and used exclusively for EML4-ALK (+) lung cancers." (PMID 33466277, 2021). "Gene expression profiles were generated from a signaling pathway screen in EML4-ALK-regulated lung cancer cells and verified by qPCR and Western blotting." (PMID 34090412, 2021). "The first oncogenic fusion detected in lung cancer was EML4–ALK, resulting from a small inversion on the short arm of chromosome 2, that promotes the fusion of EML4 N-terminal with ALK (exon 20)." (PMID 33916986, 2021). "More importantly, when H2228 cells, an EML4–ALK fusion-containing lung cancer cell line, were immunostained with an anti-ALK antibody, we observed similar spherical condensates, suggesting that endogenous EML4–ALK also undergoes LLPS." (PMID 33976114, 2021). "Accumulating studies have proven that lung cancers harboring oncogenic alterations in ROS1 or EML4-ALK respond poorly to immunotherapy, whereas KRAS mutations are associated with an improved response to immunotherapy." (PMID 34497760, 2021). "Positive p-STAT6 staining was detected in the primary tumors of 5 out of 7 EML4-ALK-positive lung cancer patients, while p-JAK2 appeared in all seven primary tumors." (PMID 34090412, 2021).
lung cancer (continued). "Consistently, a Japanese cohort also showed an upregulation of the blood coagulation pathway in EML4-ALK-positive lung cancer." (PMID 33761896, 2021). "Three major variants (v1: E13;A20, v2: E20;A20, and v3: E6;A20) account for more than 90% of lung cancers patients with fusion of ALK and EML-4 (Echinoderm Microtubule-Associated Protein-Like 4) genes." (PMID 34686712, 2021). "As a next step, EML4-ALK lung cancer cell lines from humans were used to clarify in depth how exactly the induction of EMT contemporaneously with the acquisition of resistance to crizotinib takes place." (PMID 33572278, 2021). "A CRISPR/cas9 adenoviral vector was used to generate a mouse model of EML4-ALK positive lung cancer." (PMID 33806977, 2021). "In the present study, we focused on lung cancers harboring the EML4-ALK fusion protein, found in 2–9% of all NSCLC patients." (PMID 33907223, 2021). "As they share the same essential growth driver due to constitutively activated ALK, we investigated the applicability of ALK inhibitors, such as in conventional therapy of lung cancer harboring EML4-ALK, to thyroid cancer." (PMID 33878728, 2021). "Our results suggest that the JAK2-STAT signaling pathway plays an important role in the occurrence and development of lung cancer mediated by EML4-ALK." (PMID 34090412, 2021). "To determine the effect of oncogenic EML4-ALK on the biological behaviors of lung cancer cells, we assessed the cell apoptosis following EML4-ALK knockdown in H2228 cells or expression of the EML4-ALK variant 3 in HEK293 cells." (PMID 34090412, 2021). "Immunohistochemistry analyzed the cellular localization of p-STAT6, p-JAK2, and ALK in EML4-ALK-positive lung cancer tissues." (PMID 34090412, 2021). "The mouse model with Eml4-Alk-mediated lung cancer has been developed after Eml4-Alk inversion (chromosomal rearrangement) with CRISPR/Cas9 system." (PMID 34901007, 2021). "The echinoderm microtubule-associated protein-like 4 (EML4)-anaplastic lymphoma kinase (ALK) fusion gene, a driver mutation in lung carcinoma, is fairly common in lung adenocarcinoma but rare in large cell neuroendocrine carcinoma (LCNEC)." (PMID 34377493, 2021). "Next, we used the programmable knockdown capacity of the Cas13a machinery to target ALK RNA in EML4-ALK fusion transcripts in H3122 lung cancer cells, with the goal of decreasing cell viability and providing proof-of-principle of a novel therapeutic approach." (PMID 33255340, 2020). "These cell lines were derived from the parental H3122 cells and STE‐1 cells, a patient‐derived lung cancer cell line described in, both of which carry the EML4‐ALK (E13;A20) translocation." (PMID 32558295, 2020). "In this study, we discovered a cell cycle dysregulation and a vulnerability of EML4‐ALK lung cancer cells to the pan‐CDK inhibitors alvocidib and dinaciclib, as well as the CDK7/12 inhibitor THZ1." (PMID 32558295, 2020). "One of the most successful examples is echinoderm microtubule like‐4‐anaplastic lymphoma kinase (EML4‐ALK)‐mutant lung cancer, which affects 4–5% of lung cancer patients." (PMID 32558295, 2020). "In conclusion, transcriptional inhibition with the described CDK inhibitors offers a new way to induce apoptosis in EML4‐ALK lung cancer cells." (PMID 32558295, 2020). "In a recent study on ALK FISH-positive lung cancer, patients with canonical fusion partners involving EML4 were found to have better overall survival (20.6 months vs. 5.4 months, p < 0.01) than those with noncanonical ALK fusions." (PMID 33019710, 2020). "To generate a challenging lung cancer mouse model, we focused on the Eml4-Alk chromosomal rearrangement, which is a complex mutation found in many solid human tumors, especially non-small cell lung cancers." (PMID 32591530, 2020). "Of note, in vitro and in vivo tumor suppressive functions of CLU were also confirmed on lung cancers driven by two other important oncoproteins, namely mutant EGFR driven and EML4-ALK driven lung cancers." (PMID 33052230, 2020).
lung cancer (continued). "Taken together, the cell viability and knockdown results indicated that the Cas13a effector effectively knocked down the fusion oncogene EML4-ALK in the H3122 lung cancer cell line." (PMID 33255340, 2020). "Most unique to lung cancer is a fusion between ALK and the microtubule associated protein like 4 EML4." (PMID 32283832, 2020). "Further, we extended these findings to other ALKomas, i.e. EML4-ALK-harbouring lung cancer and NPM-ALK-harbouring lymphomas." (PMID 31937834, 2020). "H2228 human lung carcinoma cells that express EML4-ALK fusion showed M phase delay in the presence of TAE684 at about IC50 concentrations." (PMID 32344689, 2020). "Certain genes are tumor-type specific: EML4-ALK fusions have been detected in lung cancer samples, and nucleophosmin (NPM1)-ALK fusions were found in anaplastic large cell lymphoma (ALCL)." (PMID 31513617, 2019). "The identification of inversions of echinoderm microtubule-associated protein-like 4 (EML4) with ALK in Japanese women with lung cancer led to the development of drugs targeting EML4-ALK fusions." (PMID 30886831, 2019). "Direct proof of the oncogenic potential of EML4-ALK in lung cancer pathogenesis has been demonstrated in mice." (PMID 29455675, 2018). "Recently, a more comprehensive view of EML4-ALK signaling in lung cancer was revealed using a combination of phosphoproteomics, tandem-affinity precipitation and RNAi." (PMID 29455675, 2018). "This type of genetic engineering approach was successfully used to study oncogenic chromosomal rearrangements in mouse models of human cancers, such as the EML4-ALK oncogene in lung cancer." (PMID 30009155, 2018). "The importance of PI3K-AKT signaling in EML4-ALK rearranged lung cancer is uncertain as other studies observed activated ERK and STAT3 but not AKT in the same cell lines." (PMID 29455675, 2018). "PCR amplification, using primers located in the kinase domain of ALK, confirmed the presence of ALK in our resistant cells and in EML4-ALK positive lung cancer cells, which served as a positive control." (PMID 30290811, 2018). "We also observed associations between fusion status and expression level in well-known fusions, such as RET–NTRK1 in thyroid cancer, EML4–ALK in lung cancer, and DNAJB1–PRKACA in the FLC subtype of liver cancer." (PMID 29617662, 2018). "We examined ciliation in the EML4-ALK-fusion-positive lung cancer cell line NCI-H2228 (which is highly sensitive to the ALK inhibitor NVP-TAE684) and a drug-resistant derivative generated through chronic NVP-TAE684 exposure." (PMID 29874589, 2018). "This is the first report demonstrating synergistic effects of combined TAE684 and radiotherapy in EML4-ALK positive lung cancer cells." (PMID 29304828, 2018). "As a TKI-relevant example, analysis of the degree of tumor shrinkage in response to ALK inhibitors in patients with EML4-ALK positive lung cancer revealed a highly significant positive correlation with overall and progression-free survival." (PMID 29458371, 2018). "For this purpose, we have recently developed an in vivo imaging model for brain tumors, which mimics brain metastasis using EML4‐ALK lung cancer cells." (PMID 29125233, 2017). "These control samples corresponded to an engineered standard sample which harbored two well-characterized fusion transcripts, EML4-ALK (E6:A20) and CCDC6-RET (C1:R12), and the human lung cancer cell line H2228 (EML4-ALK; E6:A20)." (PMID 28970558, 2017). "The Archer® FusionPlex®ALK, RET, ROS1 v2 allowed the expected detection of the fusion breakpoints present in the samples: EML4-ALK (E6:A20) and CCDC6-RET (C1:R12) for the commercialized sample, and EML4-ALK (E6:A20) for the human lung cancer cell line H2228." (PMID 28970558, 2017). "The efficacy of DNA-based vaccination was also observed in lung cancer xenograft models with EML4-ALK as well as in a TFG-ALK transgenic lung cancer mouse model." (PMID 29189709, 2017).
lung cancer (continued). "Initially found in non-small cell lung cancer (NSCLC), EML4-ALK fusion has been regarded as an important event in the development of lung cancer and an indication for the application of crizotinib (an ALK inhibitor)." (PMID 28535796, 2017). "Since the discovery of the EML4-ALK fusion oncogene in lung cancer in 2007, targeted therapies aiming to inhibit the constitutively activate ALK kinase domain have been the main focus for cancer therapy." (PMID 29189709, 2017). "EML4-ALK fusion genes have attracted great attention from oncologists focusing on lung cancer since two related landmark studies were published." (PMID 28535796, 2017). "Prominent examples include Gleevec targeting BCR-ABL in chronic myelogenous leukemia, and crizotinib targeting EML4-ALK in lung cancer." (PMID 28415823, 2017). "Few reports have discussed the imaging features of EML4-ALK-positive lung cancer, although many such tumors present as solid masses." (PMID 26964537, 2016). "EML4-ALK-positive lung cancer is a primary malignant lung tumor consisting of cells that with a characteristic abnormal configuration of the DNA where the EML4 gene is fused to the anaplastic lymphoma kinase (ALK) gene." (PMID 27070423, 2016). "The imaging features of EML4-ALK-positive lung cancer are often discussed in relation to their histopathological findings." (PMID 26964537, 2016). "This is comparable to a previous study’s concordance reported between FISH and sequencing using much greater sequencing depth (843X) detecting an EML4-ALK fusion in lung cancer." (PMID 27093186, 2016). "In non-small cell lung cancer (NSCLC), echinoderm microtubule-associated protein-like 4 (EML-4) and kinesin family member 5B (KIF5B) account for the majority of ALK gene rearrangement lung cancer." (PMID 26966027, 2016). "Here, we analyzed the mutational frequency of EGFR and KRAS gene, as well as EML4-ALK rearrangement, and summarized the clinicopathological characters of Chinese lung cancer patients." (PMID 26739511, 2016). "A recent study using CRISPR/Cas9-mediated in vivo EML4-ALK engineering in mice also showed that the mice expressing EML4-ALK were born with lung cancer, indicating that EML4-ALK is definitely a strong cancer promoter and a good therapeutic target." (PMID 26802023, 2016). "MSP and DNA sequencing assay results indicated the presence of SOCS3 promoter methylation in H2228 cells as well as in three cases of seven EML4-ALK-positive lung cancer tissues." (PMID 27666544, 2016). "Here, we show a case of lung cancer with EML4-ALK positive that shows GGN for CT with potentially aggressive." (PMID 26964537, 2016). "The methylation status of the SOCS3 promoter in EML4-ALK-positive H2228 lung cancer cells and lung cancer tissues was detected by methylation-specific PCR (MSP) analysis and verified by DNA sequencing." (PMID 27666544, 2016). "We consider that EML4-ALK-positive lung cancer is often highly progressive and that careful follow-up is therefore essential in these patients." (PMID 26964537, 2016). "Because the EML4-ALK detected in our fusion processing is well known in lung cancer, crizotinib and ceritinib were recommended as potential drugs for AYA09." (PMID 26925973, 2016). "We herein report a case of EML4-ALK-positive lung cancer presenting with a GGN along with a review of the relevant literature, including histopathological findings and imaging features." (PMID 26964537, 2016). "Similar efficacy was observed in EML4-ALK positive lung cancer patients treated with crizotinib and second-generation ALK inhibitors." (PMID 25789627, 2015). "The CRISPR-Cas9 system has also been used to induce a specific chromosomal rearrangement, the Eml4-Alk inversion, in somatic cells of adult animals to generate a mouse model of Eml4-Alk-driven lung cancer." (PMID 25984354, 2015). "RT-PCR is a good candidate method for detecting EML4-ALK in blocks of pleural effusion cells from lung cancer patients." (PMID 25785456, 2015).